INS (insulin)
Diseases named in the same sentence as INS in open-access papers (continued):
Sharing a sentence is not in itself a finding about the gene and the disease.
breast cancer (continued). "Our rationale for the analyses is based on the predominant fat cell component of the mammary gland, the tissue’s responsivity to insulin and leptin, and its anatomical correspondence to breast cancer." (PMID 37047583, 2023). "Most invasive breast cancers have insulin/IGF-1R signaling activation, and xentuzumab in combination with paclitaxel can effectively reduce metastasis incidence and metastatic burden in preclinical mouse models." (PMID 36755926, 2023). "It is likely, therefore, that the net outcome for breast cancer development depends on the balance between the opposing actions of insulin, oestradiol, progesterone, glucocorticoids, and other alternative pathways." (PMID 37337133, 2023). "At cellular level, chronic insulin exposure facilitates oestradiol-dependent growth of ER + breast cancer cell lines, while glucocorticoids suppress this insulin induction." (PMID 37337133, 2023). "Metformin counteracts insulin-stimulatory effects and leads to anti-proliferative and anti-migratory effects in primary breast cancer cells." (PMID 36849958, 2023). "Breast cancer also shares miRNA involvement with diabetes, with miRNA-375 impacting insulin secretion, while also being shown to have tumour-suppressing qualities, being downregulated in malignant cells." (PMID 37628874, 2023). "Previous clinical study has found that women with T2DM treated with long-term subcutaneous insulin injection have an increased incidence of breast cancer." (PMID 35299970, 2022). "The mechanistic basis for a ketogenic diet reducing breast cancer incidence and overall disease burden lies within decreased insulin signaling and overall reduced inflammation seen with prolonged nutritional ketosis." (PMID 35752704, 2022). "When soluble klotho was applied to the breast cancer cells, the activation of insulin and IGF-1 pathway, resulting in reduced proliferation, was identified." (PMID 35666743, 2022). "For instance, it stimulates fusion of secretory vesicles, controls endothelial cell function, facilitates insulin signaling in hepatocytes, and prevents cell growth in breast cancer." (PMID 35156900, 2022). "Insulin stimulates the overexpression of leptin which sets up an autocrine loop to stimulate breast cancer cell growth." (PMID 35406618, 2022). "The mechanism of action of insulin and its importance for normal metabolic regulation, as well as its impact on breast cancer, have been reviewed extensively." (PMID 36556357, 2022). "Proteomic screening and network analyses of breast cancer cell lines stimulated with either IGF-1 or insulin suggested signaling interactions between the two pathways." (PMID 36568144, 2022). "A recent study has shown that Akt activation by insulin increases the NAMPT expression in human breast cancer MCF-7 cells." (PMID 35326191, 2022). "Insulin signaling in various cell models (colorectal, liver, and breast cancer cells) was reported to be a potent transcriptional inducer that regulates SREBP-1 through Akt, mTORC1, and Gsk3β." (PMID 35631531, 2022). "Insulin has mitogenic effects on breast tissue, and insulin receptors are frequently over-expressed in breast cancer cells." (PMID 35371885, 2022). "ADIPOQ/adiponectin is an abundant adipocytokine secreted by AT and adipocytes of breast cancer tissue and possesses insulin sensitizing, anti-inflammatory function, and antiatherogenic performances." (PMID 35701840, 2022). "In support of a critical role for insulin in cancer progression, high IR expression is a poor prognostic factor in lung cancer, breast cancer, and colon cancer." (PMID 35244142, 2022). "In the case of breast cancer, evidence revealed that insulin stimulates the proliferation of some human breast cancer cell lines in vitro by activating both the PI3K/Akt and the MAPK signaling pathways." (PMID 35933633, 2022). "Particularly for breast cancer, these mechanisms include the lowering of hormones such as estrogen and the avoidance of high insulin levels with PA." (PMID 35406528, 2022).
breast cancer (continued). "For instance, GPER is overexpressed in seminomas, melanomas, some ovarian cancers, some lung cancers (NSCLC), and in insulin-resistant endometrial cancer models and in most of the breast cancer (particularly TNBC) models reported in this paper." (PMID 36558071, 2022). "The impact of targeting IGF-dependent signaling for breast cancer therapy on insulin-dependent regulation of metabolic homeostasis will also be discussed." (PMID 36556357, 2022). "This review is an attempt to establish the applications of insulin mimetic vanadium compounds for the treatment of breast cancer by AMPK activation and PTP1B inhibition pathways." (PMID 35159385, 2022). "Women diagnosed with early-stage breast cancer taking metformin had 22% lower fasting insulin levels and had several improved metabolic factors such as lower total cholesterol." (PMID 35326592, 2022). "Several reports have shown that administration of a low carbohydrate ketogenic diet to mice resulted in significant reduction of blood glucose and insulin levels, reduced breast cancer growth and metastasis and prolonged survival." (PMID 35917304, 2022). "In vitro studies of colorectal, prostate, and breast cancer lines showed that glargine, detemir, lispro, and aspart all stimulated cell proliferation more than regular human insulin." (PMID 35158824, 2022). "A recent clinical study demonstrated that KD therapy played a beneficial role by reducing TNF- α, and insulin, and increasing IL-10 in breast cancer patients." (PMID 36438725, 2022). "Breast cancer: PA reduces body fatness, circulating estrogen levels, insulin resistance and inflammation, improves insulin sensitivity, moderates insulin fasting levels as well as IGF-1 secretion, decreases oxidative stress and enhances DNA repair mechanisms." (PMID 33525638, 2021). "By studying signaling in the earlier time points, we hope to unravel some early response differences of the breast cancer cells to single IGF1 or insulin stimulation." (PMID 34191793, 2021). "Associations of each 10-unit increase in the 21-gene RS with breast cancer recurrence by insulin and the IGF axis biomarker levelsa." (PMID 34456877, 2021). "In this sense, a group ascribed the antiproliferative activity of metformin against human breast cancer to its ability to impair insulin/IGF-1-mediated signaling pathway." (PMID 34535145, 2021). "There is also evidence that the IGF/insulin signaling pathway functions differently depending on ER status in breast cancer." (PMID 34606580, 2021). "Results of the KEGG analysis showed that these target genes were involved mainly in the insulin signaling pathway, insulin secretion, breast cancer, oocyte division, and the thyroid hormone signaling pathway." (PMID 33665012, 2021). "Insulin increases cytotoxicity of 5-FU in breast cancer cells through activation of apoptotic and autophagic pathways." (PMID 34034636, 2021). "A previous study observed a significant improvement in circulating biomarkers such as insulin levels after exercise training in obese breast cancer survivors." (PMID 34135964, 2021). "Benefits for aerobic exercise on breast cancer outcomes likely accrue via improvements in adipokine profile, insulin sensitivity, mitochondrial and immune function as well as reduction in chronic inflammation." (PMID 34638355, 2021). "The insulin/insulin receptor (IR) signaling pathway plays an important role in breast cancer progression by stimulating the RAS/RAF/MAPK kinase/ERK cascade in breast tissues, which results in tumor cell proliferation, survival and migration." (PMID 34384462, 2021). "The therapeutic use of insulin and its analogues in diabetic patients was shown to correlate with a higher incidence of breast cancer, however these conflict with another study reporting the inhibitory effect of insulin on tumor growth." (PMID 34225729, 2021).
breast cancer (continued). "A direct mitogenic role is supported by studies from other groups, as well as our in vitro studies, which report that insulin promotes proliferation, migration, and invasion of breast cancer cells and promotes breast cancer progression." (PMID 33495474, 2021). "They provide support for a potential indirect of metformin on breast cancer outcomes (mediated by reductions in insulin and other metabolic markers)." (PMID 34103538, 2021). "Elevated insulin levels can cause high insulin growth factor-1 (IGF-1) bioavailability, leading to the occurrence and proliferation of breast cancer." (PMID 33842335, 2021). "Skeletal muscle is a key component of body composition in breast cancer because a decrease in skeletal muscle induces chronic inflammation and insulin resistance." (PMID 33557032, 2021). "We investigated the effects of exercise training on Wnt signaling and insulin sensitivity in breast cancer survivors (BCS)." (PMID 32616883, 2020). "This is consistent with our previous report showing that both SphK1 and SphK2 are important for insulin-induced growth in breast cancer cells." (PMID 32796926, 2020). "Associations of biomarkers of insulin and IGF axis with all-cause mortality, breast cancer-specific mortality, and breast cancer recurrencea." (PMID 32974138, 2020). "The strengths of this study include the prospective study design, relatively large sample size, high percentage of complete documents of breast cancer prognosis events, as well as comprehensive measurements of biomarkers of insulin and the IGF axis." (PMID 32974138, 2020). "In the case of breast cancer more specifically, the mechanisms that have been purposed as key factors in this interaction include leptin, adipose tissue inflammation, insulin and insulin growth factor(IGF-1) and sex hormones." (PMID 33371214, 2020). "The other reason contributing to progression of breast cancer is decrease of plasma levels of sex hormone binding globulin related to insulin, which results in increase of endogenous estrogen and androgen levels." (PMID 35582045, 2020). "Evidence for a causal influence of these metabolic factors comes from preclinical data showing that breast cancer cells are stimulated by insulin and certain adipokines and are vulnerable to glucose restriction." (PMID 32819413, 2020). "In MCF-7 human breast cancer cell line, estradiol has potentiating effects on insulin signaling via increasing the expression of the insulin receptor substrate-1 (IRS-1)." (PMID 32774370, 2020). "Insulin promotes the growth of breast cancer cells in nude mice, and increases the proliferation and migration of MCF-7 human breast cancer cell line by upregulating insulin receptor substrate 1 and activating the Ras/Raf/ERK pathway." (PMID 32631390, 2020). "IL-6 regulates insulin, resistin and estrogen, and thereby directly affects breast cancer development." (PMID 32824813, 2020). "In our current study, the effects of insulin on EMT in two different phenotype breast cancer cells lines, MDA-MB-231 and MCF-7 were assessed." (PMID 32631390, 2020). "Our results suggest that insulin promotes breast cancer cell invasion, migration by upregulating expression of NR2F2, which plays a critical role in insulin-mediated breast cancer cell invasion, migration through its effect on EMT." (PMID 32631390, 2020). "Signaling pathways activated by insulin also drive biologically aggressive breast cancer and predict poor survival in women with breast cancer." (PMID 33194937, 2020). "This grapefruit flavanone inhibited both basal and insulin-stimulated glucose uptake in two breast cancer cell lines (MCF-7 and T-47D)." (PMID 31936350, 2020). "Dr. Pamela Goodwin has been a pioneer in the use of metformin for lowering insulin and breast cancer chemoprevention; she has developed some of the first trials testing metformin." (PMID 33194937, 2020). "Insulin is a potent hormone that activates many pathways that drive aggressive breast cancer biology." (PMID 32153503, 2020).
breast cancer (continued). "Metformin clearly lowers insulin-signaling; signaling pathways activated by insulin are known to drive biologically aggressive breast cancer and predict poor survival in women with breast cancer." (PMID 33194937, 2020). "We found that NR2F2 played a crucial role in insulin-mediated EMT in breast cancer cells by increasing vimentin and N-cadherin and inhibiting E-cadherin levels." (PMID 32631390, 2020). "The ultimate response to a KD in humans with breast cancer therefore demands controlled trials for those with normal as well as abnormal insulin sensitivity." (PMID 33270630, 2020). "In the current study, we studied the effect of NR2F2 on insulin-mediated EMT in the breast cancer cells lines, MDA-MB-231 and MCF-7." (PMID 32631390, 2020). "Reduced exposures to insulin and insulin-like growth factors (IGFs) are potent stimulators of cell growth related to the development of breast cancer." (PMID 32664915, 2020). "There are studies reporting higher serum insulin levels in breast cancer patients compared to the healthy control." (PMID 32133259, 2020). "The stimulation of non-small cell lung, pancreatic and breast cancer cell lines, which express the IR, with insulin led to proliferation in vitro." (PMID 33604295, 2020). "Increased levels of fasting serum insulin is associated with distant tumor recurrence and death in women with early breast cancer and high levels of fasting insulin is an indicator of a poor prognosis in women with breast cancer." (PMID 32631390, 2020). "In line with that, insulin-resistant hyperinsulinemic animal models inoculated with mouse mammary carcinoma cells present advanced mammary tumors." (PMID 32695336, 2020). "Leptin and insulin increase Sam68 expression in breast cancer cell lines, with an increase in its tyrosine phosphorylation." (PMID 32033341, 2020). "This is in agreement with luminal breast cancers responding directly to an increase in circulating insulin through altered transmembrane IRs." (PMID 31703648, 2019). "Exercise has been shown to increase the lean body mass of breast cancer patients, and decrease the fat percentage, body mass index, and insulin level with improved muscle strength and cardiopulmonary functions." (PMID 31121916, 2019). "One of the most important mechanisms behind the observed association between central obesity and breast cancer is the systemic release of pro-inflammatory cytokines, which causes insulin resistance, and alterations in the insulin-initiated signaling pathways, which are linked to BC development." (PMID 31661891, 2019). "High serum insulin level increases breast cancer growth and invasion via activation of the PI3K pathway, and improved insulin resistance can reduce metastasis in mice." (PMID 31398937, 2019). "Previous larger physical activity randomized controlled trials with breast cancer survivors have found that the effects of physical activity on the insulin pathway are stronger among obese survivors." (PMID 31605514, 2019). "In a randomised controlled trial examining the effects of exercise in overweight or obese breast cancer survivors, circulating biomarkers (insulin, IGF‐1, adiponectin and leptin) were significantly improved post‐intervention, compared to usual care." (PMID 31016867, 2019). "Concordantly, blockade of the insulin signaling pathway inhibited the growth and metastasis in several cancer types including breast cancer both in vitro and in vivo." (PMID 31548560, 2019). "C-peptide, insulin, leptin, and other metabolic hormones are assumed to play roles in breast cancer development; though, results are inconsistent." (PMID 31292496, 2019). "Accumulated FFA, cholesterol, triglycerides, estrogen, leptin, insulin, interleukins, and chemokines together promote breast cancer initiation, proliferation, and invasion." (PMID 31398937, 2019). "Insulin acts as a breast cancer cell mitogen directly and indirectly via insulin-like growth factors (IGFs)." (PMID 31555644, 2019).
breast cancer (continued). "Obesity also affects breast cancer in women by secretion of some adipokines, which are also called as “released hormones”, especially estrogen, adiponectin, leptin, and insulin." (PMID 31398937, 2019). "For example, results from a meta-analysis of five randomized controlled trials of postmenopausal breast cancer survivors showed that exercise after cancer therapy reduced levels of serum insulin growth factors and binding proteins." (PMID 31694687, 2019). "The potential carcinogenic effect of insulin has been demonstrated in vitro in terms of increased proliferation in human breast epithelial cells and breast cancer cell lines." (PMID 30092829, 2018). "The practice of physical exercises has been highlighted as an important protective factor against breast cancer, since it reduces serum levels of estrogen, insulin, leptin, and proinflammatory cytokines and increases adiponectin." (PMID 30112392, 2018). "In total, 75% of breast cancer patients show activation of insulin/IGF-1 receptor signaling and this correlates with increased macrophage infiltration and advanced tumor stage." (PMID 29367764, 2018). "Naringenin (10 μM), a grapefruit flavanone, inhibited both basal and insulin-stimulated glucose uptake in two breast cancer cell lines (MCF-7 and T47D cells)." (PMID 29713632, 2018). "Among various factors, insulin plays an important role by binding to the insulin receptors expressed on breast cancer cells and activate signaling through PI3K/Akt and Ras/MAPK pathways, which finally leads increased tumour proliferation." (PMID 30034522, 2018). "Another hormonal factor that links obesity and breast cancer is the high circulating levels of insulin in obese women, as a consequence of the increased pancreatic synthesis to compensate for their insulin resistance." (PMID 29415446, 2018). "Under an obese state in breast cancer, leptin interacts with molecular effectors such has estrogen, insulin, IGF-1 and inflammatory cytokines, which impacts various stages of breast cancer from initiation to metastatic progression." (PMID 30567335, 2018). "Metformin improves systemic glucose homeostasis, which lowers the level of insulin, a well-known mitogen for insulin-sensitive breast cancer cells." (PMID 28496098, 2017). "Additional studies suggest that tumors in obese breast cancer patients, particularly ER/PR-negative tumors, are dependent of growth factors such as insulin, insulin growth factor 1 (IGF1), and leptin." (PMID 28607775, 2017). "In this study, we found that 60 μM DHA, but not AA and OA, reduced p-SREBP-1, m-SREBP-1, and FASN protein expression in insulin or E2 stimulated human breast cancer MCF-7 cells." (PMID 29282029, 2017). "Previous studies reported that insulin and miR-29a can promote breast cancer invasion and metastasis." (PMID 28427228, 2017). "Insulin is an important molecule in metabolism, and insulin and the insulin signaling pathway play an important role in breast cancer occurrence and progression." (PMID 28427228, 2017). "The mitogenic effects of insulin and IGF-I are well known and stand at the basis of the association between T2D and an increased risk of breast cancer incidence and mortality." (PMID 28785242, 2017). "Insulin promotes breast cancer growth and invasion by activating the following two major signaling pathways: the PI3K/AKT pathway and the RAF/MAPK pathway." (PMID 28427228, 2017). "miR-29a plays crucial roles in decreasing glucose-stimulated insulin secretion, as well as in regulating breast cancer cell proliferation and EMT." (PMID 28427228, 2017). "In this study, we demonstrated that insulin promotes miR-29a expression in breast cancer cells, regulates ER-positive breast cancer cell growth and invasion and participates in the insulin signaling pathway." (PMID 28427228, 2017). "Many previous studies have confirmed that insulin can promote breast cancer cell growth and proliferation." (PMID 28427228, 2017).